LHFPL6 (LHFPL tetraspan subfamily member 6)
Synonyms: LHFP; MGC22429
Tractability: Antibody: UniProt predicts a signal peptide or a membrane-spanning region.
Gene: Protein-coding gene on chromosome 13 (39,209,116 to 39,603,735, reverse strand). Ensembl gene ENSG00000183722.
Subcellular location: Membrane
Subcellular location (Human Protein Atlas): Nucleoli
Gene Ontology:
Cellular component: membrane
Genetic constraint (gnomAD): Loss-of-function variants: 9 observed, 19.36 expected, observed/expected ratio (o/e) 0.46, 90% interval 0.28 to 0.81. The upper end of that interval is the gene's LOEUF score, 0.81, which puts it in group 3 of 6, group 1 being the genes least tolerant of losing a copy. Missense variants: 218 observed, 259.72 expected, observed/expected ratio (o/e) 0.84, 90% interval 0.75 to 0.94. Synonymous variants: 105 observed, 102.41 expected, observed/expected ratio (o/e) 1.03, 90% interval 0.87 to 1.21.
Homologues: Orthologues: chimpanzee LHFPL6 (100% identical), macaque LHFPL6 (100% identical), pig LHFPL6 (98% identical), guinea pig LHFPL6 (98% identical), mouse Lhfpl6 (97% identical), rabbit LHFPL6 (97% identical), rat Lhfpl6 (97% identical), dog LHFPL6 (96% identical), zebrafish lhfpl6 (86% identical), tropical clawed frog lhfpl6 (84% identical). Paralogues in human: LHFPL1 (63% identical), LHFPL2 (29% identical), LHFPL5 (27% identical), LHFPL3 (26% identical), LHFPL4 (26% identical), LHFPL7 (24% identical).
Diseases named in the same sentence as LHFPL6 in open-access papers:
LHFPL6 is named in the same sentence as 15 diseases in open-access papers, as found by Europe PMC text mining. Sharing a sentence is not in itself a finding about the gene and the disease. The quoted sentences say what the papers report.
lipoma (13 papers, 2008 to 2025). A benign, usually painless, well-circumscribed lipomatous tumor composed of adipose tissue. "Finally, the LHFP gene (also known as the LHFPL6 gene) encodes a member of the lipoma HMGIC fusion partner protein, which is a tetraspan transmembrane protein first identified in lipomas." (PMID 38397906, 2024). "LHFPL6 (tetraspanin subfamily member 6), localized to chromosome 13q, is a member of the lipoma HMGIC fusion partner gene family, which was reported as a translocation partner of the high mobility group A2 (HMGA2) gene." (PMID 41249628, 2025). "The top SNP rs1409440 (ORmeta ≈ 2.01, Pmeta ≈ 4 x 10–6) is located upstream of LHFPL6, which is thought to be involved with lipoma formation." (PMID 36227936, 2022). "Therefore, genes known to be related to lipomas were also considered as potential candidate genes, and included SPRYD7, LHFPL6, RCBTB2, RCBTB1, and CDK4." (PMID 39719593, 2024). "LHFPL tetraspan subfamily member 6 protein, also known as lipoma HMGIC fusion partner is encoded by LHFPL6 gene with no confirmed function, although a recent study evaluated LHFPL6 as a bone mass regulator in mice." (PMID 33815092, 2021).
gastric cancer (3 papers, 2013 to 2025). A primary or metastatic malignant neoplasm involving the stomach. "LHFPL6 also served as a risk factor for unfavorable survival in gastric cancer, which was consistent with our study." (PMID 41249628, 2025). "In addition, LHFPL6, with three putative transmembrane domains, is a candidate prognostic biomarker and therapeutic target for gastric cancer." (PMID 36015309, 2022).
systemic lupus erythematosus (1 paper, 2021). An autoimmune multi-organ disease typically associated with vasculopathy and autoantibody production. "A copy number variation of LHFPL6 associates with average daily gain in cattle, while its rs4073643 associates with systemic lupus erythematosus in the Chinese population." (PMID 33472578, 2021).
cancer (7 papers, 2013 to 2025). A tumor composed of atypical neoplastic, often pleomorphic cells that invade other tissues. "Canonical CTNNB1 p.Ser45Pro missense mutation, as well as several other cancer-related genes (e.g., PML, HSP90AA1, BAZ1A, ARHGAP5, LHFPL6), were detected in the PT sample." (PMID 35860547, 2022). "Apart from CTNNB1, we’ve identified several cancer-related gene mutations, including PML, HSP90AA1, BAZ1A, ARHGAP5, LHFPL6 in the primary tumor of HB, which may also contribute to the carcinogenesis of HB." (PMID 35860547, 2022).
tumor (5 papers, 2010 to 2025). "In conclusion, this study performed an integrative analysis of CAF cell subpopulations in CRC and demonstrated that LHFPL6 is associated with CAF-mediated tumor progression, establishing LHFPL6 as a promising prognostic biomarker and potential therapeutic target for CRC." (PMID 41249628, 2025). "We found that LHFPL6 silencing in CAFs significantly attenuated SW480 tumor proliferation, invasion, and migration." (PMID 41249628, 2025). "Functional experiments using CAF-tumor co-culture models demonstrated that LHFPL6 knockdown suppressed SW480 malignant behaviors, as evidenced by reduced proliferation, migration, and invasion." (PMID 41249628, 2025). "Beyond CRC, these mechanistic insights into how LHFPL6 in CAFs modulates tumor behavior may have broader implications for understanding CAF biology in diverse malignancies." (PMID 41249628, 2025). "This may be because LHFPL6 ablation in CAFs remodels the tumor-permissive niche into a growth-restrictive microenvironment, suggesting a potential molecular mechanism involved in regulating tumorigenesis." (PMID 41249628, 2025). "Third, although LHFPL6 shows promise as a potential therapeutic target, CAF-targeted therapies have encountered translational barriers, including tumor heterogeneity and variable treatment responses." (PMID 41249628, 2025). "Finally, multivariate Cox regression analysis identified that LHFPL6 is an independent prognostic factor for CRC (HR = 5.889, 95% CI: 1.367–25.364, p = 0.017), after adjusting for age, gender, and tumor stage." (PMID 41249628, 2025). "In addition, multivariate Cox regression analysis identified that LHFPL6 is an independent prognostic factor for CRC, after adjusting for age, gender, and tumor stage." (PMID 41249628, 2025). "In addition, we identified a prognostic CAF-specific gene, LHFPL6, and confirmed that LHFPL6 knockdown attenuated SW480 malignancy, suppressing proliferation, migration, and invasion using CAF-tumor co-culture models." (PMID 41249628, 2025).
LHFPL6 also shares sentences with these, for which no sentence is quoted: colorectal cancer (2 papers); Anxiety (1); bruxism (1); deafness (1); epilepsy (1); hypospadias (1); Lipedema (1); prostate carcinoma (1); psoriasis (1); schizophrenia (1).